BMI1 (BMI1 proto-oncogene, polycomb ring finger)
Diseases named in the same sentence as BMI1 in open-access papers (continued):
Sharing a sentence is not in itself a finding about the gene and the disease.
cervical carcinoma (continued). "After PCR amplification and sequencing, by comparison to known cDNA sequences in GeneBank, we identified BMI-1 from T7 cDNA phage library of mixed cervical carcinoma tissues." (PMID 22132147, 2011). "Does AL exert its inhibitory effects on cervical cancer through BMI1/SATA3 signaling axis?" (PMID 33927214, 2021). "It showed that AL could induce autophagic death in cervical cancer cells by inhibiting BMI1 expression." (PMID 33927214, 2021). "AL may target BMI1 to induce autophagic cell death and exert potent inhibitory effects on cervical cancer." (PMID 33927214, 2021). "Therefore, we suggest that AL plays a pivotal role in inhibiting BMI1 in the tumorigenesis of cervical cancer and is a potential therapeutic agent for cervical cancer." (PMID 33927214, 2021). "Therefore, we assume that AL inhibited EMT in cervical cancer cells to promote autophagy by inhibiting BMI-1 expression." (PMID 33927214, 2021). "Finally, tissue array studies demonstrated that expression of Bmi1 increased with the severity of cervical dysplasia, suggesting a potential role in the progression of cervical cancer." (PMID 23592995, 2013). "Furthermore, immunohistochemical (IHC) staining of cervical cancer tissue specimens demonstrated increased Bmi1 levels in invasive lesions." (PMID 23592995, 2013). "Additionally, Bmi1 overexpression has been significantly correlated with tumor size, clinical stage, and regional lymph node metastases in cancers of the cervix." (PMID 23592995, 2013). "Recently, BMI-1, a member of the PcG group, has been found to be over-expressed in a variety of human cancers, including human cervical carcinoma resulting in the induction of auto-antibodies that our studies indicate may be clinical useful." (PMID 22132147, 2011). "BMI-1 mRNA or protein levels were over-expressed in cervical carcinoma cell lines." (PMID 22132147, 2011). "In conclusion, we highlight the significance of BMI-1 autoantibody in cervical cancer." (PMID 22132147, 2011). "Therefore,in this study, we employed efficient methodologies to determine levels of BMI-1 autoantibodies in patient sera from a cDNA T7 phage display library constructed with mixed cervical carcinoma tissues." (PMID 22132147, 2011). "Levels of BMI-1 autoantibody were also significantly correlated with disease progression (P = 0.001), suggesting that BMI-1 could be a new candidate for screening test in cervical cancer." (PMID 22132147, 2011). "In our study, we identified BMI-1 from a T7 phage cDNA library of mixed cervical carcinoma tissues." (PMID 22132147, 2011). "Thus, the miR-376c-3p and the BMI1 factor may represent novel biomarkers for diagnosis as well as for target therapy in cervical cancer patients." (PMID 32154165, 2020). "Given the evidence demonstrating increased expression of Bmi1 in immortalized cells and tumorigenic cervical cancer cells and the observation that even invasive cervical tumors overexpress Bmi1, we examined whether Bmi1 expression correlated with the severity of cervical cancer progression." (PMID 23592995, 2013). "Bmi-1 and CD44v6 may be used to predict the prognosis of cervical carcinoma." (PMID 23691455, 2012). "Similarly, silencing of BMI-1 can inhibit the metastatic capability of cervical cancer cells." (PMID 21851624, 2011). "Whether BMI-1 autoantibodies can be used as a biomarker for cervical carcinoma is unclear." (PMID 22132147, 2011). "While, miR-16 overexpression suppresses proliferation in cervical cancer and NSCLC by targeting BMI1, and mTORC, and triggering apoptosis and autophagy." (PMID 37767112, 2023). "This interaction between miR-16 and BMI1 is critical in promoting apoptosis in NSCLC and cervical cancer." (PMID 37767112, 2023). "Ectopic PIWIL1 overexpression in cervical cancer cells promotes tumor sphere formation by regulating the stem cell-related transcription factors OCT4, NANOG, KLF4, and BMI1, thus conferring resistance to cisplatin." (PMID 35083142, 2021).
cervical carcinoma (continued). "Cell culture experiments suggest that expression of BMI1, a core component of PRC1, is reduced in E6/E7 transduced HFKs and BMI1 expression is inversely correlated with HPV titer in cervical carcinomas." (PMID 29069809, 2017). "Taken together, these results suggest that EGFP-positive cervical cancer cells also express some stem cell-related factors, such as OCT4, Bmi1, and ALDH1." (PMID 24489842, 2014). "Given its significance in regulating autophagy and apoptosis, targeting the BMI1/ATM/miR-16 circuit may hold therapeutic potential in treating NSCLC and cervical cancer by modulating cell survival and death responses." (PMID 37767112, 2023). "BMI1 and KLF4 expression levels were found to be elevated in ALDH-high cervical cancer cells that display high stem-like features compared to the ALDH-low cell population, indicating that BMI1 and KLF4 may be CCSC markers." (PMID 27343550, 2017). "Indeed, Bmi1 mRNA expression is increased in cervical cancer compared to corresponding noncancerous tissues." (PMID 23592995, 2013). "Although Bmi1 was increased in immortalized, non-tumorigenic HFKs, we queried whether its expression might be altered in cervical cells and during the progression to cervical cancer." (PMID 23592995, 2013).
endometrial cancer (25 papers, 2005 to 2025). Primary or metastatic malignant neoplasm involving the endometrium (mucous membrane that lines the endometrial cavity). "Bmi-1 is critically implicated in carcinogenesis and chemoresistance, and the modulation of its expression has emerged as a therapeutic strategy in the endometrial cancer field." (PMID 32059385, 2020). "In conclusion, we demonstrate for the first time that loss of BMI-1 expression is significantly correlated with vascular invasion and loss of hormone receptors in endometrial carcinomas." (PMID 18475299, 2008). "Increased expression of Bmi1 was shown to be associated with poor prognosis in endometrial cancer." (PMID 40433700, 2025). "Moreover, a decrease in BMI-1 expression caused the inhibition of migration and invasion potential of endometrial cancer cells." (PMID 36497428, 2022). "Furthermore, Bmi-1 expression is strongly associated with the enhanced invasive activity of endometrial carcinoma cell lines." (PMID 32059385, 2020). "miR-200c-3p (miR-200c) suppresses EMT and dephosphorylates AKT in endometrial cancer cells by targeting the BMI1 proto-oncogene polycomb ring finger (BMI-1) gene, which is reversed by miR-200c inhibition." (PMID 36835100, 2023). "Our study suggested that depending on glucose availability and molecular context, BMI-1 can differently affect the activation of the AKT pathway by regulation of PHLPP isoform expression in endometrial cancer cells." (PMID 36497428, 2022). "In endometrial cancer cells, the BMI1 transcript level was higher in high glucose concentration but the Bmi-1 protein level was higher in low glucose compared to high glucose." (PMID 36497428, 2022). "In endometrial cancer cells, miR-194-5p inhibits epithelial–mesenchymal transition by targeting Bmi-1." (PMID 35008751, 2021). "BMI‐1 was observed to be up‐regulated in a variety of tumours, but data on the expression of BMI‐1 protein in endometrial cancer are very limited and inconsistent." (PMID 31863623, 2020). "Despite the fact that overexpression of BMI‐1 is involved in promotion of invasion and metastasis of several cancers, its role in endometrial cancer seems to be different." (PMID 31863623, 2020). "In endometrial carcinoma, a second-generation inhibitor of Bmi-1 (PTC-028) decreased the invasion of endometrial cancer cells and potentiated caspase-dependent apoptosis." (PMID 32059385, 2020). "Our analyses shed new insights into molecular mechanisms of BMI‐1, PHLPP and pAKT interdependence underlying endometrial cancer progression, and they offer implications for prognosis and drug selection strategies." (PMID 31863623, 2020). "Bmi-1 levels are significantly elevated in both type I and type II models of endometrial cancer cell lines." (PMID 32059385, 2020). "Our current findings suggest that low BMI‐1 expression in endometrial cancer can be a potential biomarker of aggressive tumour and poor prognosis in endometrial cancer patients." (PMID 31863623, 2020). "Our results suggest that high Bmi-1 levels can be an independent prognostic marker in endometrial carcinoma." (PMID 32059385, 2020). "Bmi-1 levels in endometrial carcinoma G2 and G3 were higher than those in normal endometrial tissues in the secretory and proliferative phases." (PMID 32059385, 2020). "Bmi-1 and cyclin A expression showed a tendency to increase in endometrial carcinoma in comparison to normal tissues." (PMID 32059385, 2020). "Recently, the promise of anti-Bmi-1 strategies for the treatment of endometrial carcinoma has been detected." (PMID 32059385, 2020). "Several studies have revealed the involvement of BMI1 in tumor cell invasion in gastric, hepatocellular, pancreatic, and endometrial carcinomas, as well as the correlation between BMI-1 up-regulation and chemotherapy resistance." (PMID 32742599, 2020). "Bmi-1 exhibited a similar expression pattern to cyclin A, and both proteins showed a tendency towards upregulation in endometrial carcinoma in comparison to normal tissues." (PMID 32059385, 2020).
endometrial cancer (continued). "Overexpression of Bmi-1 has been detected in many human cancer types, including endometrial carcinoma." (PMID 32059385, 2020). "Our study suggested the usefulness of Bmi-1 expression as a prognostic marker in endometrial carcinoma tissues." (PMID 32059385, 2020). "We examined Bmi-1 expression in endometrial carcinoma tissue and normal tissue (in the secretory and proliferative phases) using immunohistochemical staining." (PMID 32059385, 2020). "Bmi-1 expression determined by immunohistochemistry was significantly higher in endometrial carcinoma than in normal endometrial tissues, which is in agreement with previous studies." (PMID 32059385, 2020). "Several reports have also identified Bmi-1 protein overexpression in endometrial carcinoma; however, the relationship between Bmi-1 expression and its significance as a clinicopathological parameter is still insufficiently understood." (PMID 32059385, 2020). "Stable silencing of BMI-1 in invasive mesenchymal endometrial cancer cells was shown to downregulate vimentin, and significantly reduced cell invasion in vitro." (PMID 28968963, 2017). "In endometrial cancer cells, miRNAs can activate or attenuate EMT and CSC by targeting PTEN and other EMT-associated genes, such as Twist1, ZEB1 and BMI-1." (PMID 25141911, 2014). "In endometrial cancer cells, miR-194 has been reported to inhibit self-renewal factor BMI-1, reduce cell invasion and inhibit epithelial-mesenchymal transition (EMT)." (PMID 22829924, 2012). "The aims of this study was to determine the roles of BMI-1 in inducing EMT of endometrial cancer (EC) cells and the possible role of miRNA in controlling BMI-1 expression." (PMID 21851624, 2011). "On the basis of this background, we have investigated the expression of BMI-1 in endometrial carcinomas in relation to histopathologic features, markers of cell-cycle regulation, and hormone receptors, as well as patient outcome." (PMID 18475299, 2008). "We studied the expression of polycomb group (PcG) protein BMI-1 in a large population-based patient series of endometrial carcinomas in relation to clinical and molecular phenotype." (PMID 18475299, 2008). "Bmi1 expression was found to be similar in both types of endometrial cancer." (PMID 40433700, 2025). "In endometrial cancer, a direct correlation was found between Bmi-1 expression and Akt expression; interestingly, lower levels of both Bmi-1 and the Akt pathway were associated with more aggressive cancer phenotypes, which stands in contrast to most other cancers." (PMID 36726797, 2023). "In our study, we wanted to verify our hypothesis that depending on glucose availability and molecular context, BMI-1 can differently affect the activation of the AKT pathway by regulation of PTEN or PHLPP isoform expression in endometrial cancer cells." (PMID 36497428, 2022). "Our results showed that in both endometrial cancer cells BMI-1 may be involved in EMT because inhibition of BMI-1 by PTC-209 caused a decrease in SNAIL and SLUG expressions and an increase in CDH1." (PMID 36497428, 2022). "The objective of our study was to determine the expression of BMI‐1 protein in endometrial cancer and determine whether its expression inversely correlates with PTEN gene expression and positively correlate with AKT phosphorylation level." (PMID 31863623, 2020). "Molecular targeted therapy using Bmi-1 is also being evaluated for endometrial carcinoma." (PMID 32059385, 2020). "Several reports have identified Bmi-1 overexpression in endometrial carcinoma." (PMID 32059385, 2020).
endometrial cancer (continued). "Recently, anti-Bmi-1 treatment has emerged as a promising strategy for endometrial carcinoma." (PMID 32059385, 2020). "Accordingly, the present study aimed to clarify whether immunohistochemical staining for Bmi-1 in human endometrial carcinoma and normal endometrial tissues can be used as a prognostic and cell proliferation marker." (PMID 32059385, 2020). "However, we found lower expression of BMI‐1 in samples of more advanced endometrial carcinomas (stage III/IV) compared to less advanced tumours (stage I and II)." (PMID 31863623, 2020). "Similarly, the Bmi-1 nuclear labeling index was significantly higher in G2 and G3 endometrial carcinoma than in proliferative phase tissue." (PMID 32059385, 2020). "In endometrial cancer, miR-194 was also found to have a protective effect, increasing levels of E-cadherin and reducing levels of vimentin, thus inhibiting cellular invasion via its regulation of the protein BMI-1." (PMID 26909612, 2016). "Also, 57 fresh frozen endometrial carcinomas were studied for the relationship between BMI-1 protein expression, BMI-1 mRNA level, and activation of an 11-gene signature reported to represent a BMI-1-driven pathway." (PMID 18475299, 2008). "Thus, our results suggest that BMI-1 may impact the regulation of AKT activity both via PTEN or PHLPPs expression; this is associated with the proliferation and metastasis ability of endometrial cancer cells." (PMID 36497428, 2022). "Moreover, the results of our previous studies on endometrial cancer suggested that BMI-1 may be involved in the regulation of PHLPP." (PMID 36497428, 2022). "Therefore, anti-Bmi-1 strategies may represent a promising targeted approach in patients with advanced or recurrent endometrial cancer, a population where treatment is very challenging." (PMID 32059385, 2020). "Understanding the relationship between PI3K/AKT pathway and BMI‐1 function may contribute in the future to the development of therapeutic approaches that will be better adapt to the molecular context and the specificity of endometrial cancers." (PMID 31863623, 2020). "However, to date, there has been limited research into the role of Bmi-1 in endometrial cancer." (PMID 32059385, 2020). "Furthermore, we tested whether Bmi-1 expression advances in different grades of endometrial carcinoma." (PMID 32059385, 2020). "The aim of our study was to determine the role of BMI-1 in glucose and molecular context-dependent regulation of PHLPP expression and AKT kinase activity in endometrial cancer cells." (PMID 36497428, 2022). "BMI-1 inhibition impacts on genes involved in SNAIL, SLUG, and CDH1 and reduces endometrial cancer cells’ migratory and invasive potential." (PMID 36497428, 2022). "Thus, new endometrial cancer treatment strategies may potentially target elevated Bmi-1." (PMID 32059385, 2020). "B lymphoma mouse Moloney leukemia virus insertion region 1 (BMI-1) activates EMT in many human cancers and is overexpressed in endometrial cancer." (PMID 26356073, 2015). "Alterations in the AKT pathway are common in endometrial cancers but the role of BMI-1 in AKT activity regulation is not yet fully recognized." (PMID 36497428, 2022). "This study aimed to determine the role of BMI-1 inhibition by PTC-209 in the regulation of PHLPPs expression and AKT kinase phosphorylation in high and low conditions in endometrial cancer cells differing in PTEN status and the influence of BMI-1 on migratory and invasion potential of these cells." (PMID 36497428, 2022). "In endometrial cancer, high BMI1 expression was frequently observed in patients without vascular invasion." (PMID 34442383, 2021).
endometrial cancer (continued). "Engelsen et al9 studied BMI‐1 expression by immunohistochemistry in a large group of samples from endometrial cancer patients, but benign endometrial tissue samples were not compared to malignant tissue in this study." (PMID 31863623, 2020). "In our preliminary experiments using Ishikawa and HEC-50B derived from patients with low-grade and high-grade endometrial carcinoma cell lines, Bmi-1 was highly expressed in both cell lines (data not shown)." (PMID 32059385, 2020). "Endometrial cancer cells expressing endogenous BMI-1 show increased invasive ability in comparison to those not expressing endogenous BMI-1." (PMID 26356073, 2015). "Impact of BMI‐1 on PHLPPs is not restricted to endometrial cancer HEC1A cells." (PMID 31863623, 2020). "Moreover, we suggest that assessment of combined expression of BMI‐1, PTEN and PHLPP may be especially helpful in endometrial cancer prognosis." (PMID 31863623, 2020). "Bmi-1 expression showed no notable differences among International Federation of Gynecology and Obstetrics (FIGO) stages in endometrial carcinoma." (PMID 32059385, 2020).